NR4A3 (nuclear receptor subfamily 4 group A member 3)
Description:
Transcriptional activator that binds to regulatory elements in promoter regions in a cell- and response element (target)-specific manner. Induces gene expression by binding as monomers to the NR4A1 response element (NBRE) 5'-AAAAGGTCA-3' site and as homodimers to the Nur response element (NurRE) site in the promoter of their regulated target genes (By similarity). Plays a role in the regulation of proliferation, survival and differentiation of many different cell types and also in metabolism and inflammation. Mediates proliferation of vascular smooth muscle, myeloid progenitor cell and type B pancreatic cells; promotes mitogen-induced vascular smooth muscle cell proliferation through transactivation of SKP2 promoter by binding a NBRE site (By similarity). Upon PDGF stimulation, stimulates vascular smooth muscle cell proliferation by regulating CCND1 and CCND2 expression. In islets, induces type B pancreatic cell proliferation through up-regulation of genes that activate cell cycle, as well as genes that cause degradation of the CDKN1A (By similarity). Negatively regulates myeloid progenitor cell proliferation by repressing RUNX1 in a NBRE site-independent manner. During inner ear, plays a role as a key mediator of the proliferative growth phase of semicircular canal development (By similarity). Also mediates survival of neuron and smooth muscle cells; mediates CREB-induced neuronal survival, and during hippocampus development, plays a critical role in pyramidal cell survival and axonal guidance. Is required for S phase entry of the cell cycle and survival of smooth muscle cells by inducing CCND1, resulting in RB1 phosphorylation. Binds to NBRE motif in CCND1 promoter, resulting in the activation of the promoter and CCND1 transcription (By similarity). Also plays a role in inflammation; upon TNF stimulation, mediates monocyte adhesion by inducing the expression of VCAM1 and ICAM1 by binding to the NBRE consensus site (By similarity). In mast cells activated by Fc-epsilon receptor cross-linking, promotes the synthesis and release of cytokines but impairs events leading to degranulation (By similarity). Also plays a role in metabolism; by modulating feeding behavior; and by playing a role in energy balance by inhibiting the glucocorticoid-induced orexigenic neuropeptides AGRP expression, at least in part by forming a complex with activated NR3C1 on the AGRP-glucocorticoid response element (GRE), and thus weakening the DNA binding activity of NR3C1. Upon catecholamines stimulation, regulates gene expression that controls oxidative metabolism in skeletal muscle (By similarity). Plays a role in glucose transport by regulating translocation of the SLC2A4 glucose transporter to the cell surface. Finally, during gastrulation plays a crucial role in the formation of anterior mesoderm by controlling cell migration. Inhibits adipogenesis (By similarity). Also participates in cardiac hypertrophy by activating PARP1 (By similarity).
Synonyms: CHN; CSMF; MINOR; NOR1
Tractability: Small molecule: a high-quality ligand is known; it belongs to a druggable protein family. PROTAC: ubiquitination databases record sites on it; its protein half-life has been measured; a small molecule that binds it is known.
Target class: Transcription factor; Nuclear hormone receptor subfamily 4; Nuclear hormone receptor subfamily 4 group A member 3; Nuclear receptor; Nuclear hormone receptor subfamily 4 group A
Gene: Protein-coding gene on chromosome 9 (99,821,855 to 99,866,891, forward strand). Ensembl gene ENSG00000119508.
Subcellular location: Nucleus
Pathways (Reactome):
Gene expression (Transcription): Nuclear Receptor transcription pathway; RUNX1 regulates genes involved in megakaryocyte differentiation and platelet function
Gene Ontology:
Molecular function: DNA-binding transcription activator activity, RNA polymerase II-specific; protein binding; protein kinase binding; cAMP response element binding; DNA binding; DNA-binding transcription factor activity, RNA polymerase II-specific; nuclear glucocorticoid receptor binding; nuclear receptor activity; nuclear steroid receptor activity; protein homodimerization activity; RNA polymerase II cis-regulatory region sequence-specific DNA binding; DNA-binding transcription activator activity; DNA-binding transcription factor activity; histone acetyltransferase binding; sequence-specific DNA binding; transcription coactivator binding; zinc ion binding
Biological process: negative regulation of inflammatory response; platelet-derived growth factor receptor signaling pathway; positive regulation of D-glucose transmembrane transport; positive regulation of monocyte aggregation; positive regulation of transcription by RNA polymerase II; positive regulation of vascular associated smooth muscle cell migration; positive regulation of vascular associated smooth muscle cell proliferation; regulation of smooth muscle cell proliferation; cellular respiration; cellular response to catecholamine stimulus; cellular response to corticotropin-releasing hormone stimulus; cellular response to leptin stimulus; common myeloid progenitor cell proliferation; energy homeostasis; fat cell differentiation; gastrulation; intracellular signal transduction; mast cell degranulation; negative regulation of transcription by RNA polymerase II; positive regulation of cardiac muscle hypertrophy; positive regulation of epithelial cell proliferation; positive regulation of feeding behavior; positive regulation of mast cell activation by Fc-epsilon receptor signaling pathway; positive regulation of mast cell cytokine production; positive regulation of smooth muscle cell proliferation; and 6 more
Cellular component: chromatin; nucleoplasm; nucleus; transcription regulator complex
Genetic constraint (gnomAD): Loss-of-function variants: 13 observed, 47.26 expected, observed/expected ratio (o/e) 0.28, 90% interval 0.18 to 0.44. The upper end of that interval is the gene's LOEUF score, 0.44, which puts it in group 1 of 6, group 1 being the genes least tolerant of losing a copy. Missense variants: 646 observed, 721.53 expected, observed/expected ratio (o/e) 0.9, 90% interval 0.84 to 0.95. Synonymous variants: 342 observed, 311.3 expected, observed/expected ratio (o/e) 1.1, 90% interval 1 to 1.2.
Homologues: Orthologues: chimpanzee NR4A3 (99% identical), macaque NR4A3 (98% identical), pig NR4A3 (95% identical), rabbit NR4A3 (95% identical), dog NR4A3 (94% identical), guinea pig NR4A3 (94% identical), rat Nr4a3 (93% identical), mouse Nr4a3 (92% identical), tropical clawed frog nr4a2 (56% identical), zebrafish nr4a3 (55% identical), Drosophila melanogaster Hr38 (47% identical), Caenorhabditis elegans nhr-6 (26% identical). Paralogues in human: NR4A2 (58% identical), NR4A1 (46% identical).
Diseases named in the same sentence as NR4A3 in open-access papers:
NR4A3 is named in the same sentence as 146 diseases in open-access papers, as found by Europe PMC text mining. Sharing a sentence is not in itself a finding about the gene and the disease. The quoted sentences say what the papers report.
acute myeloid leukemia (20 papers, 2013 to 2025). Acute myeloid leukemia (AML) is a group of neoplasms arising from precursor cells committed to the myeloid cell-line differentiation. "The dual NR4A1 and NR4A3 knockout mice rapidly develop acute myeloid leukemia, and in blood-derived cancers, NR4A1 and NR4A3 exhibit tumor suppressor-like activity." (PMID 40332813, 2025). "First, we tested the association between differentiation status of leukemic cells and NR4A3 expression using two large clinical datasets from patients with different acute myeloid leukemia (AML) subtypes." (PMID 36040481, 2022). "Studies in the mouse models have shown that the deletion of Nur77 and NR4A3 rapidly leads to the development of acute myeloid leukemia." (PMID 34925506, 2021). "Evidence that NR4A3 expression enhances the apoptotic response of lymphoma and acute myeloid leukemia to chemotherapy support its classification as a tumor suppressor in these malignancies." (PMID 32867110, 2020). "Previous studies have suggested that NR4A3 acts as a tumor suppressor in tumorigenesis such as hematologic neoplasms, acute myeloid leukemia, lymphoma, and gastric cancer by reducing cell viability and inducing cell apoptosis." (PMID 31209222, 2019). "Null mutation of both NR4A1 and NR4A3 results in a cell-autonomous and transplantable acute myeloid leukemia (AML)-like disease characterized by proliferative expansion of hematopoietic stem cells and accumulation of undifferentiated myeloid blasts in non-hematopoietic tissues." (PMID 26938745, 2016). "Previous reports using NR4A1/NR4A3 double knock-out mice revealed a striking phenotype of early postnatal lethality arising from the development of acute myeloid leukaemia." (PMID 24223135, 2013). "Individually, both NR4A1 and NR4A2 exhibit pro-oncogenic activity in many solid tumors, whereas in many blood-derived cancers, NR4A1 and NR4A3 are classified as tumor suppressors based on the rapid development of acute myeloid leukemia observed in double knockout NR4A1−/−:NR4A3−/− mice." (PMID 38540704, 2024). "NR4A3 (nuclear receptor subfamily 4, group A, member 3) is an early immediate gene considered a possible homeostatic regulator of proliferation, apoptosis and differentiation, and tumor suppressors in rapidly lethal acute myeloid leukemia (AML)." (PMID 36101460, 2022). "The function and mechanism of action of NR4A1 in cancer cells is complex; transgenic mice in which both NR4A1 and NR4A3 (Nurr1) have been knocked out rapidly develop an acute myeloid leukemia (AML) type of leukemia and there is evidence that NR4A1 is a tumor suppressor for AML." (PMID 27144436, 2016). "NR4A3 was previously found to function as a tumor suppressor in acute myeloid leukemia cells." (PMID 27528092, 2016). "NR4A3 was identified as a tumor suppressor for acute myeloid leukemia (AML): deletion of NR4A3 led to the rapid development of AML in mice, and NR4A3 gene deletion is common in patients with AML." (PMID 37587470, 2023). "NR4A1/NR4A3 knock-out mice rapidly develop lethal acute myeloid leukemia (AML) and reduced dosage of these genes, in mice, leads to a phenotype that recapitulates myelodysplastic syndrome (MDS), a hematologic disorder with increased susceptibility to AML." (PMID 33330042, 2020). "NR4A1 and NR4A3 are silenced in human acute myeloid leukemia (AML), and abrogation of both genes in mice leads to rapid postnatal development of AML." (PMID 24086717, 2013). "A study showed that in acute myeloid leukemia (AML) cell lines and primary AML cells, the CpG site in the intragenic region that contains exon 3 of the tumor suppressor gene NR4A3 instead of the promoter region is highly methylated." (PMID 35747513, 2022). "NR4A3 is a key tumor suppressor in myeloid malignancy, mice lacking both NR4A1 and family member NR4A3 rapidly develop lethal acute myeloid leukemia (AML)." (PMID 33330042, 2020).
acute myeloid leukemia (continued). "In addition to EWSR1-FLI1 expression in Ewing sarcoma, the EWSR1 gene fuses to various genes in other cancers (e.g., EWSR1/ELF5 in acute myeloid leukemia, EWSR1/NR4A3 in extraskeletal myxoid chondrosarcomas, and EWSR1/CHOP in liposarcoma etc)." (PMID 36875767, 2023). "Knock-out mice without NR4A3 (Nor-1) and NR4A1 (Nur77) developed spontaneous acute myeloid leukemia suggesting tumor suppressing effects." (PMID 24528603, 2014).
breast carcinoma (16 papers, 2016 to 2025). "miR-665 is significantly upregulated in breast cancer tissues and promotes cancer cell proliferation, invasion, and metastasis by inhibiting NR4A3 to activate the MEK signaling pathway, thereby functioning as an oncomiR in breast cancer progression." (PMID 41230330, 2025). "A study has shown that miR-665 can activate MEK5/ERK5 signaling and promote breast cancer metastasis by suppressing NR4A3, a nuclear receptor that can inhibit MEK5 expression and activity." (PMID 37894282, 2023). "NR4A3 acts as a tumor suppressor in lung and breast cancer, favoring the activation of programmed cell death programs." (PMID 36101460, 2022). "Previously, using publicly available clinical data and patient survival analysis has been shown that having high levels of NR4A3 expression positively correlates with increased survival rates for patients with breast cancer." (PMID 35547878, 2022). "Correlation analysis in the TCGA dataset showed a non-significant correlation between methylation and expression levels of NR4A1 and 2 and a non-significant inverse correlation between methylation and expression levels of NR4A3 in breast cancer patients." (PMID 35547878, 2022). "Modulating the expression levels of NR4A1, NR4A2, and NR4A3 can be a potential therapeutic approach for breast cancer." (PMID 35547878, 2022). "Mechanistically, overexpression of NR4A3 attenuated the proliferation of breast cancer cells and promoted apoptosis by augmenting the expression of pro-apoptotic genes PUMA and Bax." (PMID 35547878, 2022). "A previous study reveals that miR-665 expression is correlated with breast cancer survival and miR-665 expression predicts poor and promotes tumor metastasis by targeting NR4A3." (PMID 33858426, 2021). "In breast cancer, miR-665 represses the expression of nuclear receptor subfamily 4 group A member 3 (NR4A3) to activate the MAPK/ERK kinase signaling." (PMID 34497766, 2021). "In the TCGA database, NR4A3 expression in breast cancers is remarkably reduced compared with that in normal breast tissues." (PMID 31209222, 2019). "Onco-suppression in breast-cancer is supported by NR4A3 up-regulation during apoptosis in MCF-7 cells." (PMID 26894976, 2016). "miR-665 targets TRIM8 to regulate the Wnt5a/β-Catenin and Caspase-3 signaling pathways in lung squamous carcinoma to promote cell proliferation and inhibit apoptosis; miR-665 is associated with poor prognosis and promotes metastasis by targeting NR4A3 in breast cancer." (PMID 38097567, 2023). "For example, miR-665 can promote breast cancer metastasis by acting on NR4A3." (PMID 35033084, 2022). "Although NR4A3-mRNA is generally down-regulated in breast-cancer relative to the normal gland, Basal contain larger amounts than Luminal-A or Luminal-B tumors, confirming the results of a study showing NR4A3 up-regulation in TN relative to Luminal breast-tumors." (PMID 26894976, 2016). "Similarly, miR-665 could predict the poor survival and facilitate the metastasis of breast cancer via the NR4A3-MEK signaling pathway." (PMID 34860853, 2021).
myxoid chondrosarcoma (16 papers, 2011 to 2025). A chondrosarcoma characterized by the presence of myxoid changes. "Extraskeletal myxoid chondrosarcoma (EMC) is characterized by hallmark chromosomal rearrangements involving NR4A3, leading to constitutive expression of NR4A3." (PMID 40563544, 2025). "Extraskeletal myxoid chondrosarcoma, typically occurring in older males, lacks a fatty component and shows recurrent chromosomal translocations involving NR4A3." (PMID 40729281, 2024). "For instance, myxoid liposarcoma is characterized by DDIT3 translocation, most commonly fused with FUS gene, while extraskeletal myxoid chondrosarcoma features a recurrent NR4A3 translocation, most frequently translocated to EWSR1 gene." (PMID 35484289, 2022). "The EWSR1 (EWS RNA binding protein 1)/NR4A3 fusion protein of extraskeletal myxoid chondrosarcoma activates PPARγ which is crucial for lipid metabolism regulation." (PMID 28800357, 2017). "NR4A2 may functionally replace NR4A3, the usual 3′ partner in extraskeletal myxoid chondrosarcoma." (PMID 38339014, 2024). "Translocations that fuse the NR4A3 and EWSR1 genes occur in a majority of extraskeletal myxoid chondrosarcomas, and the resulting EWSR1-NR4A3 fusion protein is thought to be the driver oncogene for most such tumors." (PMID 32867110, 2020). "Extraskeletal myxoid chondrosarcoma (EMC) is an extremely rare soft tissue sarcoma, marked by a translocation involving the NR4A3 gene." (PMID 29937513, 2018).
sarcoma (14 papers, 2011 to 2025). A usually aggressive malignant neoplasm of the soft tissue or bone. "EMC is an ultra-rare sarcoma sub-type, more often arising from the soft tissues, marked by specific molecular features consisting in rearrangement of the NR4A3 gene, identified in recent years and very useful to distinguish EMC from other mimics." (PMID 32967265, 2020). "EMCs are translocation sarcomas and harbor in > 90% of the cases an NR4A3 rearrangement." (PMID 36316541, 2023). "Furthermore, EWSR1 is involved in several other sarcomas, but then with different partners, for instance extraskeletal myxoid chondrosarcoma (NR4A3), clear cell sarcoma (ATF1, CREB1), and myxoid liposarcoma (DDIT3)." (PMID 23967081, 2013). "An initial diagnosis of sarcoma NOS in the abdomen and trunk was classified as ES and extraskeletal myxoid chondrosarcoma (EMC) based on the fusion genes EWSR1::FLI1 and NR4A3::EWSR1, respectively." (PMID 40755265, 2025). "Nine fusion genes were specific to particular histotypes, including SYT::SSX fusion in synovial sarcoma, EWSR1::FLI1 fusion in ES, EWSR1::NR4A3 fusion in EMC, BCOR::CCNB3 fusion in sarcoma with BCOR genetic alterations, and EWSR1::CREB3L1 fusion in sclerosing epithelioid fibrosarcoma." (PMID 40755265, 2025). "Interestingly, driver fusion genes in sarcomas favor RBPs with LCDs such as EWS/FLI1 and TAF15/NR4A3." (PMID 35954475, 2022).
gastric cancer (12 papers, 2016 to 2025). A primary or metastatic malignant neoplasm involving the stomach. "Activation of STAT3 was previously found to associate with drug resistance in GC50, and derepression of NR4A3 sensitized gastric cancer cells to cisplatin." (PMID 27528092, 2016). "PML/RARα is known to enhance STAT3 expression, and STAT3 has been reported to epigenetically silence NR4A3 expression in gastric cancer." (PMID 36040481, 2022). "Taken together, these in vitro and in vivo results indicate NR4A3 to be a potential tumor suppressor in gastric cancer." (PMID 27528092, 2016). "Taken together, aberrant JAK/STAT3 signaling epigenetically silences a potential tumor suppressor, NR4A3, in gastric cancer, plausibly representing a reliable biomarker for gastric cancer prognosis." (PMID 27528092, 2016). "A study identified NR4A3 as the target gene of STAT3 in gastric cancer." (PMID 35747513, 2022). "Our current study, however, is the first to demonstrate that activation of STAT3 could result in promoter hypermethylation and epigenetically silence another target, NR4A3, in gastric cancer." (PMID 27528092, 2016). "And NR4A3 could activate STAT3 to inhibit the progression of gastric cancer." (PMID 35747513, 2022). "Higher NR4A3 methylation could be observed in gastric cancer patients with STAT3 activation." (PMID 33886682, 2021). "In this study, we found that the putative STAT3 target, SPG20, is epigenetically silenced in gastric cancer, similar to our previous findings of two other STAT3-epigenetically silenced targets, NR4A3 and GATA3." (PMID 31194837, 2019). "By integrated experimental and bioinformatic analyses, we have previously demonstrated that depletion of STAT3 resulted in hypomethylation of STAT3 targets and tumor suppressors, NR4A3, and SPG20, in a gastric cancer cell line with constitutive activation of JAK/STAT signaling." (PMID 33886682, 2021).